RPS16 (ribosomal protein S16)
Description:
Component of the small ribosomal subunit. The ribosome is a large ribonucleoprotein complex responsible for the synthesis of proteins in the cell. Part of the small subunit (SSU) processome, first precursor of the small eukaryotic ribosomal subunit. During the assembly of the SSU processome in the nucleolus, many ribosome biogenesis factors, an RNA chaperone and ribosomal proteins associate with the nascent pre-rRNA and work in concert to generate RNA folding, modifications, rearrangements and cleavage as well as targeted degradation of pre-ribosomal RNA by the RNA exosome.
Synonyms: S16; uS9
Tractability: Small molecule: an approved drug acts on it; a structure with a bound ligand is known; a high-quality ligand is known. PROTAC: ubiquitination databases record sites on it; its protein half-life has been measured; a small molecule that binds it is known. Other modalities: a drug acting on it is in phase 2 or 3 trials.
Target class: Other cytosolic protein
Gene: Protein-coding gene on chromosome 19 (39,433,136 to 39,436,131, reverse strand). Ensembl gene ENSG00000105193.
Subcellular location: Cytoplasm; Nucleus, nucleolus
Subcellular location (Human Protein Atlas): Cytosol; Endoplasmic reticulum
Pathways (Reactome):
Metabolism of proteins: Eukaryotic Translation Termination; Formation of a pool of free 40S subunits; Formation of the ternary complex, and subsequently, the 43S complex; GTP hydrolysis and joining of the 60S ribosomal subunit; L13a-mediated translational silencing of Ceruloplasmin expression; PELO:HBS1L and ABCE1 dissociate a ribosome on a non-stop mRNA; Peptide chain elongation; Ribosomal scanning and start codon recognition; SRP-dependent cotranslational protein targeting to membrane; Translation initiation complex formation; ZNF598 and the Ribosome-associated Quality Trigger (RQT) complex dissociate a ribosome stalled on a no-go mRNA
Disease: SARS-CoV-1 modulates host translation machinery; SARS-CoV-2 modulates host translation machinery; Viral mRNA Translation
Metabolism of RNA: Major pathway of rRNA processing in the nucleolus and cytosol; Nonsense Mediated Decay (NMD) enhanced by the Exon Junction Complex (EJC); Nonsense Mediated Decay (NMD) independent of the Exon Junction Complex (EJC)
Cellular responses to stimuli: Response of EIF2AK4 (GCN2) to amino acid deficiency
Developmental Biology: Regulation of expression of SLITs and ROBOs
Metabolism: Selenocysteine synthesis
Gene Ontology:
Molecular function: protein binding; RNA binding; structural constituent of ribosome
Biological process: ribosomal small subunit biogenesis; rRNA processing; cytoplasmic translation; maturation of SSU-rRNA from tricistronic rRNA transcript (SSU-rRNA, 5.8S rRNA, LSU-rRNA); translation
Cellular component: cytoplasm; cytosol; cytosolic ribosome; cytosolic small ribosomal subunit; endoplasmic reticulum; extracellular exosome; focal adhesion; membrane; small ribosomal subunit; small-subunit processome; nucleoplasm; nucleolus; ribosome; synapse
Genetic constraint (gnomAD): Loss-of-function variants: 2 observed, 20.04 expected, observed/expected ratio (o/e) 0.0998, 90% interval 0.04 to 0.31. The upper end of that interval is the gene's LOEUF score, 0.31, which puts it in group 1 of 6, group 1 being the genes least tolerant of losing a copy. Missense variants: 129 observed, 205.11 expected, observed/expected ratio (o/e) 0.63, 90% interval 0.54 to 0.73. Synonymous variants: 95 observed, 78.56 expected, observed/expected ratio (o/e) 1.21, 90% interval 1.02 to 1.43.
Homologues: Orthologues: chimpanzee RPS16 (100% identical), dog RPS16 (100% identical), macaque RPS16 (100% identical), mouse Rps16 (100% identical), rabbit RPS16 (100% identical), tropical clawed frog rps16 (97% identical), zebrafish rps16 (97% identical), rat Rps16l1 (95% identical), rat AABR07019341.1 (92% identical), Drosophila melanogaster RpS16 (87% identical), Caenorhabditis elegans rps-16 (75% identical). Paralogues in human: MRPS9 (36% identical).
Diseases named in the same sentence as RPS16 in open-access papers:
RPS16 is named in the same sentence as 28 diseases in open-access papers, as found by Europe PMC text mining. Sharing a sentence is not in itself a finding about the gene and the disease. The quoted sentences say what the papers report.
hepatocellular carcinoma (7 papers, 2021 to 2025). A malignant tumor that arises from hepatocytes. "A previous study found an interaction between RPS16 and USP1 in hepatoma cells." (PMID 35873150, 2022).
viral infection (7 papers, 2014 to 2024). "Is the regulatory effect of let-7 on viral infection limited to RPS16, or does it also regulate viral replication through other important targets?" (PMID 35873150, 2022). "We found the predicted target sites for let-7b and let-7f in the 3’-UTR of the human RPS16 gene, which belongs to the ribosomal proteins family playing important role in virus infection." (PMID 35873150, 2022). "In our previous study, we also found that knockdown of RPS16 enhanced the expression of pTBK1 after virus infection and after poly I:C stimulation of cells, what is the specific regulatory mechanism?" (PMID 35873150, 2022). "How about the in vivo regulatory effect of RPS16 towards influenza and other virus infection?" (PMID 35873150, 2022). "Although this study leaves some shortcoming to be desired, the findings here may still provide a perspective on the potential use of let-7 and its downstream target RPS16 as targets for the treatment of viral infections." (PMID 35873150, 2022). "As ribosomal proteins were found to play important role in virus infection, we wondered whether the inhibitory effect of IAV protein expression and replication by let-7b/f is associated with RPS16." (PMID 35873150, 2022). "DEGs unique to infected cells mapped to host defense (MYD88, C3, CASP4, JAK2, and OSM), viral infection (RNASE6 and SVVORFs), and protein synthesis (RPL18 and RPS16)." (PMID 38887303, 2024). "However, no RPS16 and GAPDH bands were detected in the precipitated samples, indicating that RALY interacts with the FMDV RNA during viral infection." (PMID 38323828, 2024).
breast carcinoma (6 papers, 2017 to 2025). "RPL27A was one of the genes that are frequently co-expressed in breast cancer patients with RPS16, which was thought to be one of the targets of miR-7641." (PMID 34497807, 2021). "RPS16 and TNFSF10 as two direct targets of miR-7641 and many other ribosomal proteins that are frequently co-expressed with RPS16 in breast cancer are also deregulated by miR-7641." (PMID 34497807, 2021). "Similarly, miR-7641 inhibition in MDA-MB-231 breast cancer cells upregulated RPS16, TNFSF10, MSRB3, CDNF, ZNF616, and NBEA, downregulated CUL3, and showed no remarkable changes for PIGC and the other genes." (PMID 28827731, 2017). "Upon inhibition of miR-7641 expression, the expressions of several of the target genes (RPS16, RNF4, EMC8, and MSRB3) increased, CUL3 expression decreased, and other genes, including PIGC, remained unchanged in MCF-7 breast cancer cells." (PMID 28827731, 2017). "Our data confirmed RPS16 and TNFSF10 as two direct targets of miR-7641, while gene expression study showed that a group of genes are also deregulated by miR-7641, including many ribosomal proteins that are frequently co-expressed with RPS16 in breast cancer." (PMID 28827731, 2017).
influenza infection (3 papers, 2018 to 2022). "Interestingly, other genes include Tpc1 involved in mitochondrial transport, and RpS16 associated in humans with viral mRNA translation, and the influenza infection/life cycle." (PMID 30134827, 2018). "Our findings suggest that let-7 and its target gene RPS16 are potential targets for anti-influenza therapeutics." (PMID 35873150, 2022). "Furthermore, when silenced the expression of RPS16 in A549 cells, the expression of influenza NP was detected by western blot and the virus titer was determined by plaque forming assay." (PMID 35873150, 2022). "The results showed that when we knock down the expression of RPS16 in host A549 and BEAS-2B cell, the replication of influenza was inhibited; exogenous expression of RPS16 increased virus replication." (PMID 35873150, 2022). "Furtherly, when the RPS16 knockdown cell were treated with IFN-β neutralizing antibody after influenza A virus infection, the expression of influenza NP were increased compared with the cell treated with IgG control, indicating the increased virus replication in the cell." (PMID 35873150, 2022).
colorectal cancer (2 papers, 2020 to 2022). A primary or metastatic malignant neoplasm that affects the colon or rectum. "Ribosomal protein S16 (RPS16) is a highly conserved 40S ribosomal protein, which has been reported to be highly expressed in various cancers, such as colorectal cancer (CRC)." (PMID 35875077, 2022).
Diamond-Blackfan anemia (2 papers, 2017 to 2023). A congenital aregenerative and often macrocytic anemia with erythroblastopenia. "The diseases associated with RPS16 include Diamond-Blackfan Anemia and Descending Colon Cancer." (PMID 37482618, 2023). "According to recent publications, various systematic diseases have been attributed to RPS16, including Diamond-Blackfan Anemia and cancer." (PMID 29152097, 2017).
pancreatic cancer (2 papers, 2007 to 2020). "Notably, the only common up-regulated gene, RPS16 in ZR75-1 (down-regulated in MCF-7) correlates with its overexpression in breast, colon, prostate, liver, and pancreatic tumors." (PMID 17883861, 2007).
glioblastoma (1 paper, 2023). The most malignant astrocytic tumor (WHO grade IV). "For example, with glioblastoma, eS6 (RPS6), eS27 (RPS27), uS8 (RPS15A) and eL34 (RPL34) are known as oncogenic, whereas uL18 (RPL5), uS17 (RPS11), uS9 (RPS16) and uS13 (RPS18) are found to have a tumor-suppressive function." (PMID 37511213, 2023).
glioma (1 paper, 2021). A benign or malignant brain and spinal cord tumor that arises from glial cells (astrocytes, oligodendrocytes, ependymal cells). "RPS16 contributes to facilitate tumor progression of glioma via the PI3K/AKT signaling." (PMID 34555052, 2021).
liver cancer (1 paper, 2021). An epithelial or non-epithelial malignant neoplasm that arises from the liver. "Our current research showed that USP1 promotes the growth and migration of liver cancer cells by maintaining the stability of RPS16 protein." (PMID 34154657, 2021). "Consistent with the analysis of the TCGA database, the protein expressions of USP1 and RPS16 in liver cancer tissues are up-regulated compared with adjacent liver tissues." (PMID 34154657, 2021).
infection (27 papers, 2008 to 2025). The state of being infected such as from the introduction of a foreign agent such as serum, vaccine, antigenic substance or organism. "As previous experiment, A549 cell was infected with influenza A/WSN/1933 at 1 MOI, then test the expression of RPS16 at mRNA and protein levels at 0, 6, 12, and 24 h post infection by qRT-PCR and western blotting, respectively." (PMID 35873150, 2022). "Initially, the presence of ribosomes and specific ribosomal subunits such as RPS6, RPS16, and RPL3 and viral mRNA within these sites indicated compartmentalization of translation during infection." (PMID 38421168, 2024).
cancer (8 papers, 2017 to 2023). A tumor composed of atypical neoplastic, often pleomorphic cells that invade other tissues. "This up-regulation of RPS16 promotes the growth and migration of HCC cells by promoting the expression of Twist1 and Snail, thereby revealing the new pathological function of RPS16 in cancer." (PMID 34154657, 2021). "The data showed that inhibition of miR-7641 upregulated RPS16 in all cancer cell lines, while TNFSF10, RNF4, EMC8 and CUL3 responded irregularly." (PMID 28827731, 2017). "In addition, we analyzed the protein levels of USP1 and RPS16 in two tissue arrays containing cancer tissues and adjacent normal tissues from 90 HCC patients (obtained from Shanghai Outdo Biotech Company)." (PMID 34154657, 2021).
tumor (6 papers, 2021 to 2024). "Using qRT-PCR analyses further showed increased expression of Xpo1, Rpl12, Rps16, and Eif4a1 in RNA samples from primary prostate and lung metastatic tumor cells of TripleTg mice in comparison to those from PCa tissues of DoubleTg mice." (PMID 38336745, 2024). "Positive staining for XPO1, RPL12, RPS16, and pS6 proteins was also observed in both primary prostate and lung metastatic tumor cells developed in castrated TripleTg mice." (PMID 38336745, 2024).
RPS16 also shares sentences with these, for which no sentence is quoted: HCMV infection (5 papers); prostate carcinoma (3); B cell lymphoma (2); gastric cancer (2); lymphoma (2); co-infection (1); Colon Cancer (1); COVID-19 (1); depression (1); infectious disease (1); latent infection (1); neurodegenerative disease (1); neurological diseases (1); osteosarcoma (1); Pruritus (1).